TNF (tumor necrosis factor)
Diseases named in the same sentence as TNF in open-access papers (continued):
Sharing a sentence is not in itself a finding about the gene and the disease.
Allergy (continued). "In allergy, TNF may have dual pro-inflammatory and anti-inflammatory activities, which are likely mediated by its two distinct receptors." (PMID 30473698, 2018). "TNF antagonist and its efficacy in allergy as well as their effects on Tregs." (PMID 30473698, 2018). "It is well known that AR is a Type I hypersensitivity allergic reaction mediated through the activity of mast cells by all kinds of allergens and resulting in a degranulation and release of inflammatory mediators, such as histamine, TNF-α, and LTC4." (PMID 28327534, 2017). "In CD1 included also Pranlukast, an agent used against ashma and allergy that exerts anti-inflammatory effects because it inhibits CysLT1 receptor, nuclear factor kappa B (NFƙB) and TNFα, suggesting a possible suppressive effect on the spinal cord inflammation and neutrophil infiltration." (PMID 26807587, 2016). "Previous study found that the water extract of Moutan Cortex not only inhibited β-hexosaminidase and tumor necrosis factor-α release in IgE-mediated DNP-BSA-stimulated RBL-2H3 cells but also improved the compound 48/80-induced allergic reactions in a mouse model." (PMID 27822287, 2016). "LTC4, IL-6, IL-1, MCP-1/CCL2, and TNF-α play important roles in the development of allergic diseases, and their release and synthesis could be increased in various allergic diseases." (PMID 27200102, 2016). "Thus, allergy attacks can further weaken the endothelium already exposed to TNF-α and histamine from oxLDL-activated macrophages and mast cells." (PMID 25811595, 2015). "IL-1, IL-6 and TNF-α are the main Th1-type cytokines associated with dry eye syndrome, while the inflammatory Th2-type cytokines IL-4, IL-5 and IFN-γ tend to be increased in allergic diseases." (PMID 26588473, 2015). "In seasonal allergy, the Th2 cytokines TNF-α and IL-4 are elevated compared to Th1 cytokine levels." (PMID 23878502, 2013). "The analysis implicated a number of genes with roles in allergy and inflammation, including pro-inflammatory cytokines (IL1A, IL1B, IL6, IL8 and TNF) and factors involved in immune cell activation and recruitment (SELE, SELL, SELP, ICAM1, CSF2, CSF3, CCL2 and CXCL2)." (PMID 21067579, 2010). "Most children with experience of allergy showed decreases of the proinflammatory TNF-α." (PMID 20534153, 2010). "Our goal was to assess interactions between exposure to air pollution and single nucleotide polymorphisms (SNPs) in the β2-adrenergic receptor (ADRB2), glutathione S-transferase P1 (GSTP1), and tumor necrosis factor (TNF) genes for development of childhood allergic disease." (PMID 18709160, 2008). "The Th2 cells that are capable of producing of high levels of tumor necrosis factor-α may also be involved in inflammation in allergic diseases." (PMID 23283296, 2008). "TNF-alpha is an important mediator in allergy also for its effects on eosinophils." (PMID 15857511, 2005). "In vitro and in vivo, evodiamine and rutaecarpine may inhibit the biosynthesis of allergy-related cytokines (TNF-α and IL-4) in mast cells and basophils, suggesting that they may be effective against IgE-induced allergic diseases such as atopic dermatitis and rhinitis." (PMID 39944619, 2025). "A more recent study reported that PM could exacerbate the severity of allergic reactions in ovalbumin-sensitized C57BL/6 mice by causing eyelid edema and the upregulation of interleukin (IL)-4, IL-5, Tumor necrosis factor alpha (TNF-α), and serum immunoglobulin E." (PMID 39596177, 2024). "Furthermore, the gene expression of the allergy relevant cytokine TNFα was determined by qRT-PCR." (PMID 33777040, 2021). "This may explain the effectiveness of TNF antagonism in only certain allergy population." (PMID 30473698, 2018). "In allergy-related cytokines, Fat only led to significant increases in multiple BALF cytokines, notably IL-4, IL-5, IL-6, IL-12, IL-13, IL-17, IL-33, TNF-α, and IFN-γ, compared to the normal chow group (NC) (all P < 0.05 or P < 0.01)." (PMID 40998975, 2025).
Allergy (continued). "In the context of allergic diseases, current unmethylated CpG ODN adjuvants are designed to shift Th2-skewed allergic responses toward a Th1-biased profile to reduce allergies, but this immune activation may also increase TNF-α levels that have been associated with toxic shocks in mice." (PMID 40725003, 2025). "KEGG pathway analysis shows that the potential unique pathways of ACP treatment for allergic diseases include PI3K-Akt signaling pathway, Th17 cell differentiation, TNF signaling pathway, T cell receptor signaling pathway, etc.." (PMID 41155559, 2025). "Th1 cells upregulate cytotoxic immune responses by releasing interleukin (IL)-12, interferon (IFN) and tumor necrosis factor (TNF) and participate in the processes of delayed allergy or inflammation." (PMID 36834569, 2023). "The findings indicated an increase in the expression of allergy-related genes in the nasal mucosa, CD23 expression during T-B cell interaction, and TNF-induced HDAC11 expression." (PMID 37692890, 2023). "In patients with allergies, the c9, t11 isomer of the CLA supplement for 12 weeks improved allergy symptoms and reduced some inflammatory factors (i.e., TNF- α and IL-5), while it increased IFN-γ levels." (PMID 37644566, 2023). "First, isolated MVs (without SAEW treatment) prepared in a mixed ratio of 1:0 were added to RBL-2H3 cells, and the mRNA expression levels of the allergy-related genes HDC, FcεR1α, IL-4, and TNF-α were examined." (PMID 38282743, 2023). "Adipose tissue synthesizes and secretes a variety of cytokines and adipokines such as IL-6, TNF, TGF-β, and leptin that drive hypoinflammatory responses and have been proven to contribute to the pathogenesis of allergy." (PMID 35855823, 2022). "TNF and CCL3 are famous cytokines and broadly take part in regulating many immune cells and developing inflammatory and allergic diseases." (PMID 36531995, 2022). "In a study on the blood serum of intact rats anesthetized with TZX mixture, the levels of interleukin 1 beta (IL-1β) and tumor necrosis factor alpha (TNF-α) were barely determined, and TZX anesthesia is already used in animal models of allergic reactions." (PMID 35203719, 2022). "Given this histopathological feature, panels of immunohistochemical markers for TNF-alpha, IL-1, IL-6, IL-17, IL-23, IFN-gamma, and CD-45 were performed, confirming intense areas of inflammatory marker response typical of allergic reaction." (PMID 34576463, 2021). "After manual gating of CD4+ T, CD8+ T and NK cells according to S. Figure IIA, there was a reduction of TNF-α + IFN-γ+, IL-2+ cells in both allergy groups, reaching statistical significance only in the IgEneg allergy group." (PMID 32698761, 2020). "Whereas, late phase of the allergic reaction is recognized by the release of cytokines such as IL-13, IL-4, IL-9, IL-5, IFN-γ and TNF-α after 2 to 6 h of sensitisation." (PMID 31829185, 2019). "In the TNF-α inhibitor group, 9 patients had known contraindications for NSAID use (gastrointestinal (n = 4), renal (n = 4) and a proven allergy (n = 1))." (PMID 29689112, 2018). "Human surfactant protein-D (SP-D), an innate immune pattern recognition soluble factor, is known to modulate a range of cytokines and chemokines, such as TNF-α and TGF-β at mucosal surfaces during infection, allergy, and inflammation." (PMID 30158928, 2018). "In allergy perspective, although TNF antagonism does increase the TNFR2 levels, but other study demonstrated a functional insufficiency by TNF via TNFR2 signaling pathway." (PMID 30473698, 2018). "The markers of inflammation and allergic reaction, IFN-γ, TNF-α, IL-4, and IL-6, were suppressed, especially after treatment with 100 μg/mL ST." (PMID 29849717, 2018). "Based on these results, to determine the effects of mapracorat on allergy-related cytokines, a combination of IL-4 plus TNF-α was selected for the HConEpiC, and IL-13 plus TNF-α was used for the HConF." (PMID 23878502, 2013).
Allergy (continued). "The anti-inflammatory effects of mapracorat were determined after allergy-related chemokine/cytokine release and ICAM-1 was induced with IL-4 plus TNF-α in HConEpiC." (PMID 23878502, 2013). "Previous studies have found that due to its key role in barrier immunity and its synergistic effects with other cytokines, such as TNF-α, IFN-γ, and IL-1, IL-17 plays an important role in many skin diseases, allergic diseases such as allergic rhinitis and asthma, and inflammatory bowel disease." (PMID 38090557, 2023). "It is found that there are 50 potential targets of PLP in allergy, which were imported into the String database to establish PPI, among which the top 5 interaction relationships according to the number are: INS, TNF, CAT, MAPK1 and VEGFA." (PMID 35879791, 2022). "The results concurrently showed that PLP may regulate allergy through signal pathways such as MAPK, TNF, PI3K/Akt, apoptosis and Th cell differentiation." (PMID 35879791, 2022). "In infants without allergies, the phase pair abundance of Ruminococcaceae was negatively correlated with IL-6 and TNF-α induced by Toll-like receptor-2 (TLR-2), and the lower relative abundance of Ruminococcaceae appeared to be related to food sensitization." (PMID 35911834, 2022). "An important issue that needs to be emphasized considering in vitro tests is the fact that cytokines are determined in various conditions and various diseases; however, only certain cytokines (i.e., TNF-α, IL-2, IL-4, IL-5, IL-6, IL-10, IL-13, and IFN-γ) are important in allergic reactions." (PMID 36590449, 2022). "TNF-α and CXCL8 were reported to serve as important inflammatory cytokines by attracting neutrophils and basophils and promoting inflammatory reactions, not only in relation to allergies." (PMID 34299258, 2021). "Our findings are consistent with those reported by a clinical study where DHA + EPA (fish oil) supplementation in Th2 biased allergy prone infants showing increased Th1 cytokines (IFN-γ and TNF-α) and reduced Th2 cytokine (IL-13) to PHA (mitogen stimulating T cells)." (PMID 34790691, 2021). "To evaluate the clinical signs of allergy to dietary BSFL and FO, we investigated the skin status (TEWL and contents of moisture and oil), fecal score, and immune-related parameters (IgG, IL-10, and TNF-α) in serum." (PMID 34944285, 2021). "Furthermore, production of TNF-α and IL-6 as the inflammatory cytokines and its upstream events were investigated to understand the inhibitory mechanism of ESG against allergy and inflammation responses." (PMID 32801471, 2020). "YPFS has a certain effect on Th2-type cytokines such as (IL-4, IL-6, IL-10, and IL-17) and Th1 type cytokines such as (IFN-γ and tumor necrosis factor-α), and YPFS mainly exerts pharmacological effects such as immune regulation and anti-allergy and anti-inflammatory by acting on these cytokines." (PMID 31885639, 2019). "We demonstrated the possibility of the involvement of TNF-α inhibitors, history of allergy, and hypercalcemia in the development of IRIS in non-HIV pulmonary TB patients." (PMID 31905985, 2019). "While most murine allergy models involved the use of cholera toxin (CT) as an adjuvant, we opted for TNF-α due to its lower non-specific toxicity and the fact that as an endogenous cytokine, with well-known inflammatory consequences." (PMID 30410548, 2018). "While the expression of TNF-α, IL-6, GFAP, and SP, together with microglial activation, follows the pattern of a Th2 cell-dependent allergic reaction, the exact mechanism of their increase or function in the hippocampus is unknown at this time." (PMID 29849816, 2018). "Therefore, downregulation of iNOS, IL-2, TNF-α, and IFN-γ expression has been used to predict the favorable effects of test materials in patients with various allergic diseases." (PMID 26221169, 2015).
Allergy (continued). "Another study demonstrated increased production of tumor necrosis factor-alpha and interleukin-1 in cord blood mononuclear cells upon TLR2, TLR4, and TLR5 activation in newborns who later develop allergic diseases, suggesting a link between heightened perinatal TLR response and allergy development." (PMID 21912563, 2012). "Beyond allergy-specific models, reviews of anti-inflammatory herbs emphasize ginger’s broad capacity to suppress inflammatory pathways, including cyclooxygenase (COX), lipoxygenase (LOX), and NF-κB, and to decrease production of TNF-α, IL-1β, and other proinflammatory mediators." (PMID 41305557, 2025). "The production of interleukin (IL)-1, IL-6, IL-12, interferon (IFN)-γ, and tumor necrosis factor (TNF)-α promotes Th1 differentiation; IL-17A, IL-17F, IL-21, IL-22, and IFN-γ promote Th17 differentiation; IL-4, IL-5, IL-13, IL-9, and IL-6 promote Th2 differentiation involved in allergic reactions." (PMID 37372929, 2023). "Even in non-Th2 allergies, IL-17 induces airway epithelial cells to produce chemokines CXCL1 and CXCL8 to promote neutrophil recruitment while stimulating fibroblasts and macrophages to secrete cytokines such as GM-CSF, TNF, IL-1, IL-8, and IL-6 to enhance inflammatory responses." (PMID 35855823, 2022). "In the BBJ and UKB data sets, allergic diseases were significantly enriched in multiple gene sets in the lower layers of ‘cytokine signalling’, including IL−4, 5 and 13 involved in type 2 inflammation and IL-1,6, and TNF involved in non-type 2 inflammation." (PMID 35753705, 2022). "TNF concentrations did not change in any group, regardless of allergy or capsaicin supplementation." (PMID 31316714, 2019). "Moreover, the lower level of biological response to ceramic particles in vivo, represented by lower levels of tumor necrosis factor-alpha (TNF-α) and prostaglandin E2 (PGE2), makes ceramic components a promising solution for those patients with allergy to metal ions." (PMID 30782186, 2019). "TNF-α secretion following allergen challenge is higher in atopic asthmatics (i.e., asthmatics with allergy) than in nonatopics (asthmatics with no clearly defined allergy)." (PMID 29576747, 2018). "TNF-α could promote inflammation, leukocyte infiltration, and chemotaxis of both neutrophils and T cells, and activated mast cells secrete TNF-α that is pivotal in allergic reactions." (PMID 30469322, 2018). "We investigate specifically whether intrinsic differences in B cell ADAM10 levels, independent of Th bias, regulates allergy induction and severity and whether this regulation is associated with modulation of B cell ADAM17 and TNF and associated changes in secondary lymphoid follicular architecture." (PMID 25933166, 2015). "Although TSLP was produced in both allergy-negative and -positive patients, TSLP, TSLPR and TNF-α were all produced at significantly higher quantities in the mucosal epithelium samples of the former." (PMID 35159975, 2022). "In this study, hTMSCs secreted high amounts of IL-6 and IL-8, but not IL-10, TNF-α, or IFN-γ, irrespective of allergy state." (PMID 26376485, 2015). "The parameters for inflammatory diseases (CRP, TNFα and IL-6) and allergic diseases (IgE and eosinophil) were similarly unchanged, suggesting that ARA intake does not evoke inflammatory or allergic diseases." (PMID 22188761, 2011). "Further, we can exclude the possibility that the reduction in the two cytokines was not due to methodological errors such as lack of antibody staining or other systematic errors since other cell clusters with high expression of TNF-α and/or IFN-γ were not reduced in the allergy groups." (PMID 32698761, 2020).
diabetic nephropathy (225 papers, 2008 to 2025). "The authors suggested that diabetic nephropathy is predominantly associated with the inflammatory action of TNF-α via the TNFR2 pathway." (PMID 35328704, 2022). "A study on diabetic nephropathy also revealed that patients with type AA had higher blood TNF-α concentrations than those with type GG, and A allele carriers were 2.1 times more likely to suffer from macroalbuminuria (OR: 2.1, p < 0.001)." (PMID 35410083, 2022). "IL-9 was also strongly correlated with VEGF, TNFα and IL-6 all of which have all been previously implicated in diabetic nephropathy." (PMID 35445345, 2022). "C allele of TNF-α − 1031 T/C was associated with a significant risk for diabetic nephropathy progression." (PMID 35366956, 2022). "Among them, the IL-17 signaling pathway and TNF signaling pathway are closely associated with the occurrence and development of diabetic nephropathy." (PMID 36624863, 2022). "Generally, carriers of C allele of TNF-α-1031 T/C had significantly increased risk of diabetic nephropathy." (PMID 35366956, 2022). "Considering that TNF-α is also reported to be associated with lupus nephritis and diabetic nephropathy, it is possible that the induction of CL-1 in renal tubules is a common feature in kidney diseases characterized by inflammation and fibrosis." (PMID 35271660, 2022). "In summary, this study exposed that the C allele of -1031T/C SNP of TNF-α is concomitant with a significant risk for development of diabetic nephropathy." (PMID 32684830, 2020). "Increased circulatory and urinary levels of TNF-α have been found to be independently associated with increased proteinuria in patients with diabetic nephropathy." (PMID 26014479, 2015). "In patients with diabetic nephropathy and proteinuria, IL-6, TNF-α and MRP8/14 were significantly and independently associated with CRAE after adjustment for age, gender, BMI, glucose, 24 h SBP, and eGFR." (PMID 19232095, 2009). "Additionally, TNF rs1800629 has been linked to elevated TNF-α levels and albuminuria, an indicator of diabetic nephropathy." (PMID 39858569, 2024). "For instance, in rodent models of diabetic kidney disease, oxidative stress has been associated with increased levels of nuclear factor kappa B (NF-kB), tumor necrosis factor-alpha (TNF-α), and transforming growth factor beta-1 (TGF-β1), while antioxidant systems are impaired." (PMID 39456409, 2024). "Notably, tumor necrosis factor α (TNFα), IL-1 and IL-6 are increased in serum and urine of patients affected by diabetic nephropathy and are associated with the progression of renal injury." (PMID 36827456, 2023). "TNF-α could change glomerular hemorheology and is associated with renal hypertrophy in early stage of diabetic nephropathy." (PMID 35295847, 2022). "Furthermore, the protective effect of kaempferol against streptozotocin-induced diabetic nephropathy has been proved to be associated with the downregulation of TNF-α and IL-6." (PMID 35837376, 2022). "Trophic factors and cytokines, including vascular endothelial growth factor (VEGF), insulin growth factor (IGF), mitogenic cytokine, IL-8, IL-6, and TNF-α, have been implicated in the pathogenesis of diabetic retinopathy, diabetic nephropathy, and diabetic neuropathy." (PMID 26824041, 2016). "Moreover, TNF-α is closely associated with diabetic nephropathy and vascular dysfunction." (PMID 36646777, 2023). "Inflammatory factors such as interleukins (IL-1, IL-6, IL-18) and tumor necrosis factor (TNF-α) are activated in diabetic nephropathy, promoting kidney damage through various signaling pathways." (PMID 40698245, 2025). "Inactivation of TNF-α ameliorates diabetic neuropathy in mice, and inhibition of IL-1β significantly alleviates diabetic nephropathy." (PMID 40864768, 2025). "Studies have shown that TNF-α levels are significantly elevated in the renal tissue, serum, and urine of patients with diabetic kidney disease (DKD)." (PMID 40469439, 2025).